PTH (parathyroid hormone)
Diseases named in the same sentence as PTH in open-access papers (continued):
Sharing a sentence is not in itself a finding about the gene and the disease.
primary hyperparathyroidism (continued). "Normalization of PTH levels may influence brain metabolism and may be responsible for the postoperative improvement in cognition demonstrated in patients with primary hyperparathyroidism." (PMID 26010883, 2015). "Biochemical assessment showed a mildly elevated calcium (11.1 mg/dL), high parathyroid hormone, and a plasma aldosterone concentration/plasma renin activity ratio of 124.5 (normal < 30), compatible with primary hyperparathyroidism with a concomitant primary hyperaldosteronism." (PMID 26161274, 2015). "Thus, when the patient underwent detailed examination at age 26, she was diagnosed with asymptomatic primary hyperparathyroidism with increased parathyroid hormone activity (intact PTH)." (PMID 25889454, 2015). "Patients with primary hyperparathyroidism (pHPT) typically have elevated serum calcium values due to excessive secretion of parathyroid hormone (PTH) from enlarged parathyroid gland(s), with inappropriate cellular regulation of the PTH secretion." (PMID 26542689, 2015). "There are several other possible mechanisms which could explain the significant changes in PTH levels in response to postural changes in primary hyperparathyroidism." (PMID 25254042, 2014). "In primary hyperparathyroidism (PHPT) excessive amounts of PTH are produced." (PMID 23418495, 2013). "Therefore, we must consider primary hyperparathyroidism in differential diagnosis by analyzing blood calcium and PTH levels of patients presenting with mass in bones, particularly in the face." (PMID 23251174, 2012). "The link between PTH, hyperuricemia, and gout was observed in primary hyperparathyroidism." (PMID 22405053, 2012). "Furthermore, after PTX for primary hyperparathyroidism, a condition in which increased bone resorption is related to excessive secretion of PTH." (PMID 22919331, 2012). "Primary hyperparathyroidism and continuous administration of exogenous PTH, whether 1–84 or its active fragment 1–34, are known to produce bone resorption although primarily in cortical bone rather than in trabecular bone." (PMID 21829585, 2011). "In summary, the results of our small case series suggest that minimally invasive parathyroidectomy with Intraoperative PTH measurement is a feasible, safe, and effective method for treatment of primary hyperparathyroidism in the context of a district general hospital." (PMID 21197437, 2010). "Blood tests revealed increased levels of serum calcium of 12.8 mg/dL (normal, 9.0-10.6 mg/dL), incrased levels of parathyroid hormone (PTH) at 115 pg/mL (normal, 12-72 pg/mL), and a low serum phosphorus level of 2.4 mg/dL (normal, 2.5-4.5 mg/dL), findings suggestive for primary hyperparathyroidism." (PMID 20062698, 2009). "Hypercalcemia with high PTH suggested the diagnosis of primary hyperparathyroidism." (PMID 20108468, 2008). "Indeed, it was proven that patients with primary hyperparathyroidism (PHTP) lose the circadian rhythm for PTH, and continuous PTH secretion has also resorptive effects, predominantly in cortical bone, although with a partial preservation of trabecular bone mass and microarchitecture." (PMID 40251987, 2025). "Primary hyperparathyroidism (PHPT) is a common endocrinological disorder characterized by elevated serum calcium concentrations alongside increased or aberrantly normal levels of parathyroid hormone (PTH), attributable to hyperactivity of the parathyroid glands." (PMID 41509939, 2025). "A similar analysis was carried out to evaluate predictors of PTH levels in patients with primary hyperparathyroidism, adjusted for cholecalciferol supplements, which revealed that renal function and dietary calcium intake estimated from the questionnaires significantly affected PTH." (PMID 39963179, 2024).
primary hyperparathyroidism (continued). "Considering the data shown by our study it seems evident that restriction of calcium intake has no place in the conservative management of primary hyperparathyroidism, instead, our study favors adequate dietary calcium intake to mitigate PTH levels, regardless of the variant of PHPT." (PMID 39963179, 2024). "Indeed, primary hyperparathyroidism is often diagnosed in women, in the first decade after menopause, consistent with the known skeletal action of estrogen that neutralizes the hypercalcemic effects of excess PTH in bone." (PMID 37651007, 2023). "Workup included a laboratory examination showing elevated intact parathyroid hormone (PTH) and left arm ultrasound revealing three areas of enlarged parathyroid tissue at the transplant site, raising suspicion for the development of recurrent primary hyperparathyroidism in auto-transplanted tissue." (PMID 37485129, 2023). "This elevation in PTH while having normal vitamin D is unexplained but could indicate a lag time between correction of vitamin D after treatment and normalization of PTH since patients with primary hyperparathyroidism and CKD have been excluded." (PMID 36428888, 2022). "Normocalcemic primary hyperparathyroidism (NPHPT) is recognized as a new subclinical entity in the field of parathyroid disorders, and is characterized by increased serum PTH concentrations where serum calcium levels are within normal values, after the exclusion of other causes of high PTH." (PMID 33207657, 2020). "Though the exact mechanism of genu valgum in these children with primary hyperparathyroidism needs to be elucidated, it is proposed that elevated parathyroid hormone levels may have a direct effect on the growth plates during pubertal growth spurt resulting in genu valgum." (PMID 31102836, 2019). "The ratio of third- to second-generation assays for PTH is usually < 1 in primary hyperparathyroidism, but in rare cases, the serum concentration of PTH measured with a third-generation assay may be higher than that measured with a second-generation assay, yielding a > 1 ratio." (PMID 27812604, 2016). "Although we evaluated patients with primary hyperparathyroidism with an indication for surgery and high levels of serum calcium, this assay could be potentially helpful also in suspicious cases of primary hyperparathyroidism with borderline PTH values and mild disease." (PMID 27812604, 2016). "Targeted parathyroidectomy guided by intraoperative parathyroid hormone monitoring (IPM) through a small cervical incision has replaced traditional bilateral neck exploration (BNE) as the initial approach in the surgical treatment of primary hyperparathyroidism at many medical centers worldwide." (PMID 21776381, 2011). "Based on this background, we performed parathyroid hormone (PTH) and calcium tests, which confirmed the diagnosis of primary hyperparathyroidism." (PMID 40476723, 2025). "The diagnosis of Primary Hyperparathyroidism (PHPT) has been based on concomitantly high levels of blood total or ionized calcium (or both) and parathyroid hormone (PTH)." (PMID 40709988, 2025). "Primary hyperparathyroidism (PHPT) is a prevalent endocrine disorder characterized by elevated serum calcium and parathyroid hormone (PTH) levels." (PMID 40364052, 2025). "In the setting of primary hyperparathyroidism (PHPT), PTH secretion becomes dysregulated, leading to elevated hormone levels despite normal or high serum Ca concentrations." (PMID 41301518, 2025). "Consider PC as a diagnosis in cases of primary hyperparathyroidism with ALP > 285 IU/L, ionized calcium > 1.77 nmol/L (> 7.09 mg/dL), parathyroid lesions > 3 cm, or PTH > 3x ULN." (PMID 39011405, 2024). "Primary hyperparathyroidism (PHPT) affects approximately 1% of the population and is characterized by hypersecretion of parathyroid hormone (PTH) and serum-ionized calcium." (PMID 39064529, 2024).
primary hyperparathyroidism (continued). "The blood tests showed elevated serum calcium and parathyroid hormone (PTH) concentrations, consistent with hypercalcemic primary hyperparathyroidism." (PMID 38638336, 2024). "Primary hyperparathyroidism (PHPT) is characterized by the excessive and autonomous production of parathyroid hormone (PTH) by one or more parathyroid glands." (PMID 39040613, 2024). "Primary hyperparathyroidism (PHP) is a condition that develops as a result of increased and uncontrolled production and secretion of parathyroid hormone (PTH) from hyperfunctioning parathyroid glands (HPG)." (PMID 39608010, 2024). "After discovering extremely high serum calcium and parathyroid hormone (PTH) levels, the diagnosis of primary hyperparathyroidism (pHPT) was made and a surgical en bloc resection was performed." (PMID 37397577, 2023). "Primary hyperparathyroidism (PHPT) is characterized by abnormal elevation of serum calcium and parathyroid hormone (PTH) levels due to pathological parathyroid glands and involves multiple organ systems, including the skeletal, urinary and digestive systems." (PMID 37438472, 2023). "Primary hyperparathyroidism (PHPT) is a disease of the parathyroid glands, in which they produce excessive amounts of parathyroid hormone (PTH)." (PMID 38116316, 2023). "Patients undergoing surgery for primary hyperparathyroidism from March to November 2022 where intraoperative PTH assay was performed using the NBCL CONNECT IOPTH and the laboratory PTH assay were included (group 1)." (PMID 37693360, 2023). "The PTH values were either inappropriately normal or raised in >95% of hypercalcemic probands, consistent with a diagnosis of FHH or primary hyperparathyroidism." (PMID 36970776, 2023). "As parathyroid hormone (PTH) can be elevated because of FGF23 excess in patients with TIO, primary hyperparathyroidism is also a common misdiagnosis." (PMID 36511653, 2023). "Primary hyperparathyroidism (PHPT) is an endocrine disorder resulting from the hyperfunction of one or more parathyroid glands, with hypersecretion of parathyroid hormone (PTH)." (PMID 36382758, 2022). "As the biochemical hallmarks of FHH are elevated calcium and PTH levels, the main differential diagnosis for FHH is primary hyperparathyroidism (PHPT), a condition that is ultra-rare in pediatric patients and has never been reported in neonates." (PMID 35566721, 2022). "One of the most common endocrine diseases is primary hyperparathyroidism (PHPT), which results from excessive production of parathyroid hormone (PTH)." (PMID 36237812, 2022). "Primary hyperparathyroidism (PHPT) represents one of the most common endocrine disease, usually results from an excess of parathyroid hormone (PTH) produced from an overactive parathyroid gland." (PMID 34020602, 2021). "Primary hyperparathyroidism (PHPT) is an endocrine disorder characterized by high serum calcium levels, high parathyroid hormone (PTH) levels and low serum phosphorus concentration." (PMID 34420520, 2021). "Parathyroid hormone (PTH) levels were generally low, which can help differentiate MAS from primary hyperparathyroidism." (PMID 33732556, 2021). "While important causes such as malignancy and myeloma should be excluded, in the context of an inappropriately normal or elevated parathyroid hormone (PTH) level, a diagnosis of primary hyperparathyroidism is made." (PMID 33881757, 2021). "Disturbances in calcium metabolism among adults are often related to the secretion of parathyroid hormone (PTH), as in primary hyperparathyroidism (PHPT) and chronic hypoparathyroidism (HypoPT)." (PMID 34863037, 2021). "Osteitis fibrosa cystica is the classic manifestation of primary hyperparathyroidism (PHPT), occurs after prolonged exposure of bone to high serum parathyroid hormone (PTH) level." (PMID 33990191, 2021).
primary hyperparathyroidism (continued). "Normocalcemic primary hyperparathyroidism (NC-PHPT), the first subclinical phase of PHPT, is a new clinical stage characterized by average serum calcium concentration and elevated PTH levels." (PMID 33015068, 2020). "Furthermore, low 25(OH)D may occur from increased 25(OH)D to 1,25(OH)2D conversion by increased PTH in primary hyperparathyroidism and during treatment with PTH (teriparatide); this can occur due to increased activity of renal 1-alpha-hydroxylase, the enzyme responsible for this conversion." (PMID 32813765, 2020). "Patients with elevated serum parathyroid hormone (PTH) and calcium levels are defined as having primary hyperparathyroidism (PHPT)." (PMID 31655512, 2019). "Patients affected by primary hyperparathyroidism (PHPT), an endocrine disorder characterized by excessive release of parathyroid hormone (PTH), experience reduction of BMD, particularly at the cortical site of the distal radius." (PMID 31091695, 2019). "Primary hyperparathyroidism (PHPT) is the third most common endocrine disorder, after diabetes and thyroid diseases, characterized by an inappropriate secretion of parathyroid hormone (PTH) from parathyroid glands." (PMID 32082374, 2019). "Primary hyperparathyroidism (PHPT) is the most common disease in parathyroid glands and is accompanied by excessive secretion of parathyroid hormone (PTH)." (PMID 30123260, 2018). "Primary hyperparathyroidism (PHPT) diagnosis is challenging and is based on serum calcium (Ca) and parathyroid hormone (PTH)." (PMID 30283895, 2018). "Over-production of parathyroid hormone (PTH), or primary hyperparathyroidism (pHPT), is a common endocrine disease." (PMID 29532143, 2018). "We showed that TRCa/Ccr was high in patients with primary hyperparathyroidism (PHPT) and normal in those with SHPT despite comparably increased [PTH] in each group." (PMID 28445401, 2017). "Can CaSR expression be effectively upregulated in hypercalcemic conditions such as primary hyperparathyroidism or FHH to restore physiological control of plasma calcium levels and Ca2+o-dependent suppression of PTH secretion?" (PMID 28018229, 2016). "Primary hyperparathyroidism (PHPT) is a common endocrine disease characterized by simultaneously elevated serum calcium and parathyroid hormone (PTH) levels." (PMID 27846313, 2016). "Primary hyperparathyroidism (PHPT) was firstly diagnosed in the index case, a 41-year-old woman (serum calcium 11.65 mg/dl (8.4–10.2 mg/dl) and parathyroid hormone (PTH) 189 pg/ml (10–65 pg/ml))." (PMID 25416039, 2015). "The intact PTH–FNA concentration was 1.28×106 pg/ml, and the patient was diagnosed with primary hyperparathyroidism due to a cystic mass." (PMID 25379182, 2014). "The PTH–FNA assay was performed, and the patient was diagnosed with primary hyperparathyroidism due to a cystic mass." (PMID 25379182, 2014). "Primary hyperparathyroidism (PHPT), the third most common endocrine disorder, is characterized by excess PTH secretion, inappropriate with respect to the prevailing circulating ionized calcium concentration." (PMID 22974443, 2012). "Primary hyperparathyroidism (PHPT) is a frequent endocrine disordercharacterized by an excessive autonomous production and release ofparathyroid hormone (PTH) by the parathyroid glands." (PMID 22567348, 2011). "Together, preoperative imaging combined with intraoperative parathyroid hormone monitoring (IPM) allow for successful surgical outcomes and treatment of primary hyperparathyroidism at rates comparable to those of conventional bilateral neck exploration (BNE)." (PMID 21776381, 2011). "Fardella and Rodriguez-Portales observed a positive correlation between PTH and intracellular calcium and suggested that PTH may act as an ionophore for calcium entry into cells and perhaps react a prehypertensive condition in normotensive patients with primary hyperparathyroidism." (PMID 20049157, 2010).
primary hyperparathyroidism (continued). "Primary hyperparathyroidism (PHPT) is a disease that is characterized by elevated calcium and parathyroid hormone (PTH) levels." (PMID 20184676, 2009). "Levels of sclerostin were lower in patients with primary hyperparathyroidism compared to controls, having a negative correlation with PTH levels and being increased after PTX." (PMID 40177730, 2025). "The diagnosis of primary hyperparathyroidism is determined on the basis of raised calcium levels above normal (> 10.2mg/dL) and non-suppressed serum parathyroid hormone (PTH) levels (> 30pg/mL)." (PMID 40612282, 2025). "Unlike primary hyperparathyroidism, where PTH regulation provides feedback inhibition, sarcoid-related calcitriol production lacks this control, causing persistent hypercalcemia." (PMID 41179272, 2025). "Primary hyperparathyroidism was definitively ruled out based on the inverse correlation between serum calcium and PTH levels, along with repeatedly negative parathyroid scintigraphy findings." (PMID 41561737, 2025). "Primary hyperparathyroidism and vitamin D toxicity were ruled out by suppressed PTH and low 25- and 1,25-dihydroxyvitamin D. Granulomatous disease was not initially suspected due to normal ACE and no systemic or pulmonary features." (PMID 41179272, 2025). "Endocrinology ruled out primary hyperparathyroidism due to suppressed PTH and low 1,25-dihydroxyvitamin D < 5 pg/mL (SI: < 13 pmol/L) (reference range, 15-65 pg/mL [39-169 pmol/L])." (PMID 41179272, 2025). "Another variant or subtype of primary hyperparathyroidism is called normocalcemic primary hyperparathyroidism (NHPT), which is characterized by serum calcium persistently in the normal range, and PTH persistently elevated, after excluding any obvious or underlying causes." (PMID 39963179, 2024). "Intraoperative parathyroid hormone (IOPTH) monitoring is a critical surgical adjunct for determining the extent of surgery for primary hyperparathyroidism (PHPT), with reported false-positive and false-negative rates of up to 10%." (PMID 38662187, 2024). "Primary hyperparathyroidism is characterized by elevated calcium concentrations and a lack of portal feedback between calcium concentration and PTH secretion." (PMID 38665259, 2024). "Normal serum calcium and parathyroid hormone (PTH) levels excluded primary hyperparathyroidism, raising suspicion of a non-functional parathyroid adenoma, and SPECT/CT imaging showed that the mass was 99mTc-sestamibi-avid." (PMID 38841301, 2024). "The patient's suppressed PTH and undetectable PTHrP levels effectively ruled out primary hyperparathyroidism and humoral hypercalcemia of malignancy." (PMID 39006637, 2024). "Primary hyperparathyroidism (PHPT) is a common endocrine disorder with the biochemical signature of hypercalcemia and either raised or inappropriately normal serum concentration of parathyroid hormone." (PMID 37651007, 2023). "Certain authors, however, argue that the incidence of insulin resistance in primary hyperparathyroidism is due to the elevation of PTH, and not, as the researchers above have stated, due to the elevation of calcium." (PMID 37350980, 2023). "A five-year study in patients with mild to moderate primary hyperparathyroidism showed that cinacalcet reduced PTH level and normalized Ca+2 with no change in z-scores of areal bone mineral density (aBMD)." (PMID 33542868, 2021). "Previous studies in individuals with primary hyperparathyroidism and end-stage renal failure patients have shown positive associations between MPV and PTH; however, sex-specific aspects were not addressed." (PMID 34222377, 2021). "Included were 554 patients (67%), after exclusion of 4 with no signed consent, 10 with a suspicious primary hyperparathyroidism, 3 with elevated creatinine, and 13 with missing data of S-25(OH)D and PTH at 5 years." (PMID 32306297, 2020).